CD4 (CD4 molecule)
Diseases named in the same sentence as CD4 in open-access papers (continued):
Sharing a sentence is not in itself a finding about the gene and the disease.
infection (continued). "CCR5 expression levels and activation state may independently affect infection rates; the former by promoting entry of CCR5-tropic HIV, and the latter by increasing the permissiveness of CD4+ T cells to HIV infection, which can affect infection rates of both CXCR4- and CCR5-tropic HIV." (PMID 34899645, 2021). "Furthermore, depletion of CD4+ and CD8+ T cells in murine models produces an increase in the parasite burden and the exacerbation of chronic pathology, which indicates the importance of these subsets of cells in the control of infection." (PMID 33539379, 2021). "No CD4+ T cell exhaustion was detected in infected sheep at the chronic stage of the infection." (PMID 34215335, 2021). "To this end, we infected primary CD4+ T cells isolated from peripheral blood mononuclear cells (PBMCs) of three healthy human donors with HIV-1 (pNL4.3) and monitored HIV-1 replication by measuring the levels of p24 in the supernatant at 3 and 5 days post-infection." (PMID 34792020, 2021). "In addition to interferon signaling, the exhaustion program in CD8+ T cells has been tightly linked to defective CD4+ T cell-mediated help, a multi-faceted process in which CD4+ T cells provide support for the differentiation and maintenance of robust CD8+ memory T cell responses in infection." (PMID 33478949, 2021). "As LAG3 has been shown to restrict lung CD4+ and CD8+ T cell responses during respiratory viral infections, we also considered whether AT2 MHCII is required for LAG3-mediated T cell suppression during infection." (PMID 34183650, 2021). "Mice without CD4 + T cells exhibited significantly higher parasitaemia upon being infected with P. chabaudi compared to controls and were unable to reduce parasitaemia during the course of infection." (PMID 34666102, 2021). "Additionally, in the intestinal tract, non-CD4 T cells contain less HIV DNA than CD4+ T cells; however, the infection level of non-T leukocytes in the GALT is higher than that in the blood." (PMID 34922576, 2021). "However, during P. yoelii nonlethal (17XNL) infection, an earlier decrease of DN, DP, and CD4+ SP thymocytes and the reduced proliferation of DN and DP thymocytes were observed." (PMID 34113341, 2021). "Furthermore, we detected significant declines in CD4 Th1 and CD8 populations in only EBOV-Mayinga infection that paralleled robust apoptotic gene expression." (PMID 34484156, 2021). "Additionally, the HEU mothers from this study were not significantly affected by the infection as they showed healthy counts of CD4+ T cells and most of them had low HIV viral loads." (PMID 34409752, 2021). "Consistent with this, a single Sp19F infection did not induce lung CD4+ TRM cells." (PMID 34611166, 2021). "The TZM-bl cell line is a derivative of HeLa cells that express CD4, CCR5, and CXCR4 and contains an integrated reporter gene for firefly luciferase and E. coli β-galactosidase under the control of an HIV-1 long terminal repeat (LTR), permitting sensitive and accurate measurements of infection." (PMID 34578431, 2021). "Although the depletion of CD4+ T cells does not alter the course of the disease in the infection of C3H/HeN mice with a sublethal dose of R. conorii, adoptive transfer of immune CD4+ T cells protects these animals against challenge with a normally lethal dose of this pathogen." (PMID 34452021, 2021). "Our study revealed that similar to the GI mucosae, oral CD4 + T cells were rapidly depleted, and as one of the first comprehensive analyses of the oral microflora in SIV infection, we also observed significant modulation among two genera, Porphyromonas and Actinobacillus, early after infection." (PMID 34267278, 2021). "With the hypothesis that transmitted founder viruses (TFVs) may depend on CCR5 co-receptor expression of target cells for early infection and dissemination, we then assessed whether CCR5+ memory CD4+ T cells were initial and dominant target cells in primary SIV infection." (PMID 34960667, 2021).
infection (continued). "Thus, BALB/c mice are not intrinsically unable to induce nasal IL-17-producing CD4+ TRM cells upon infection with Bp." (PMID 33420041, 2021). "While CD4+ and CD8+ T-cells also contribute to immunity against SARS-CoV-2, several studies demonstrated the importance of SARS-CoV-2-specific neutralizing antibodies as a protection mechanism against severe infection, with S-IgG found in almost every patient after infection." (PMID 34696428, 2021). "This is mainly orchestrated by T cell activation following widespread infection of the CNS parenchyma as lack of MHC I and II in β2-Macroglobulin–/– and Aβ–/– MHV-J2.2-v1 mice or deficiency of CD4 in CD4–/– mice resulted in reduced viral clearance with limited demyelination." (PMID 34211370, 2021). "Regulatory T-cells (TREG, CD4+CD44+FoxP3+) ranged from 20% - 25% of activated CD4+ T-cells during UgCl223 infection and, unlike in lethal KN99α infections, were present at significantly lower levels compared to the predominant TH1 effector cell populations at all but the 0- and 77- day timepoints." (PMID 35186781, 2021). "Several other studies have found pre-existing CD4+ T-cell reactivity against peptides from SARS-CoV-2 in the absence of previous infection, and it has been hypothesized that these may confer some protection." (PMID 34795668, 2021). "However, baseline CD4 count and the time period between initial infection and the diagnosis amongst PLHIV in Bhutan never been evaluated." (PMID 33945664, 2021). "This difference could be a consequence of differences in the experimental systems (i.e. transfection versus infection, differences in time of HIV-1 progeny virion harvest, and quantitation methods) or differences between the cell type used (i.e. HEK293T versus CD4+ T cells)." (PMID 33476323, 2021). "One week after infection (end of Week 1), the number of circulating CD4+ and CD8+ T cells remained unaffected by the immunosuppressant treatments; values for both fell within the range for naive mice of the same age (CD4+ T cells 1124±238 cells/mm3, CD8+ T 716±173 cells/mm3; determined in-house)." (PMID 33524030, 2021). "Similarly, both the frequency and cell number of CD4+ T cell in peripheral blood did not change among the three infection schemes." (PMID 34025654, 2021). "Even though the immunization of mice with rNP alone does not represent the natural course of infection and immunity, a high titer of IgG found in immunized mice sera proves that rNP actually stimulates humoral immunity and is recognized by CD4+ cells as a prominent antigen in the mouse." (PMID 34851958, 2021). "Our data in this study showed more severe infection and diseases in SND1-/- mice, which correlated with significantly reduced Th1/17 immune responses, including lower levels of Cm-driven IFN-γ and local IL-12 production, higher levels of CD4+Foxp3+ Treg cells, and impaired function of DC." (PMID 33635920, 2021). "Overall, our results suggest that differences in the infection outcomes at the acute and chronic stages after infection with genetically different T. cruzi strains might be dictated by CD8+ and CD4+ T cell responses, including early effector and regulatory mechanisms." (PMID 34712620, 2021). "The protective efficacy in this model was primarily mediated by serum antibodies as depletion of CD4 cells at the time of infection in vaccinated or control animals had no significant impact on the vaccine efficacy, whereas adoptive hyperimmune serum transfer to naïve animals was highly protective." (PMID 33777005, 2021). "falciparum-specific IL-10 producing CD4+ T cells but not with IFNγ or TNFα producing CD4+ cells; however, these cells could not prevent infection prospectively." (PMID 34414129, 2021). "Using flow cytometry to quantify p27+ cells as a measure of infection, we found that CD4+, but not CD8+ CAR T cells could be productively infected." (PMID 33752225, 2021).
infection (continued). "In our study we did not observe an increased frequency of Tregs after clinical infection in older adults compared to youngsters, not favouring of a major role for Tregs in IL-2 consumption or reduced CD4+ memory T-cell proliferation in older adults in our study." (PMID 35822011, 2021). "However, after i.n. infection, mice lacking CD4+ T cells produced few functional anti-viral CD8+ T cells and were unable to even limit the dissemination of TKO-MCMV." (PMID 33508041, 2021). "However, our results demonstrate that HIV-containing platelets interacting with T cells at a low platelet:T cell ratio are sufficient to cause T-cell dysfunction even if this ratio does not promote CD4+ T infection." (PMID 35222352, 2021). "We found that mice depleted of CD4+ T-cells had diminished early antibody responses to CCHFV, suggesting that CD4+ T-cells may contribute to survival through support of early antibody responses to the infection." (PMID 33572859, 2021). "During the second stage, comprised of the third and fourth SIV population decay periods, B cells, CD4+ T cells, and CD8+ T cells were the strongest correlating cell types with viral Ne, signaling the influence of the adaptive immune response during chronic and end-stage infection." (PMID 34691023, 2021). "These infiltrating cells, particularly Ly6C+ monocytes, CD4+ and CD8+ T cells, all upregulated c-Rel protein levels in wild-type mice in response to infection at day 5 p.i., suggesting that c-Rel participates in their transcriptional response and may modulate the function of these cells." (PMID 34707143, 2021). "However, it is evident now that only specific members of the intestinal microbiota are able to induce antigen-specific helper CD4+ T cells in the absence of a classical infection." (PMID 34566952, 2021). "Although the sample size is small, our data suggest that detectable CD4+ T-cell reactivity is a less suitable measure of past infection than S-specific antibody levels and further, does not reliably indicate protection from infection." (PMID 34795668, 2021). "Interestingly, unlike for the infection-naïve individuals where all individuals responded similarly to each dose of vaccination, the magnitude of the CD4+ T cell response differed markedly between different convalescent individuals." (PMID 34636722, 2021). "When resting memory CD4 T cell subsets were infected with a CCR5-utilising primary HIV transmitted/founder (HIVTF) strain, they also showed significant and progressive increased p24 expression from CM to TM and EM similar to HIVBaL infection, albeit at lower overall levels." (PMID 33872331, 2021). "Third, while CD4 count and VL data were used to approximate duration of HIV infection, determining the recency of infection using validated methods (e.g., genetic sequence diversity) may have provided complimentary information to estimate the timing of HIV acquisition." (PMID 33915869, 2021). "Clearance of the infection requires CD4 T cells and appears to be independent of IFNγ." (PMID 34684248, 2021). "Note the similar frequencies of T cells responding to all three spike proteins in each donor, the clear boosting of spike-specific CD4+ T cell frequencies in infection-naïve but not convalescent individuals, and the overall higher proportion of responding CD4+ than CD8+ T cells." (PMID 34636722, 2021). "On the other hand, the absent induction of p21 in newborn CD4+ T cells could contribute to T cell-mediated immunopathology during infections, because p21 limits overactivation of T cells." (PMID 33912177, 2021). "However, how the HIV-1 accessory protein Vpr enhances infection in macrophages but not in CD4+ T cells remains elusive." (PMID 34140527, 2021). "CD4+, CD8+, and γδ subsets of T cells in protective immunity against mycobacterial pathogens predominantly function as a source of cytokines which either directly activates macrophages to kill mycobacteria or participate in the extension of other T cells involved in infection." (PMID 34290737, 2021).
infection (continued). "Importantly, in the absence of IL-13 expression, neither IL-4 nor IL-5 cytokine expression was changed in CD4+ T cells after infection." (PMID 34127548, 2021). "The infection of peripheral blood mononuclear cells with exosomes purified from HIV-1 positive individuals resulted in stimulating CD38 expression on central memory CD8+ and CD4+T cells, which activated bystander cells and facilitated viral transmission and inflammation." (PMID 34575480, 2021). "In addition to the VS, there is another type of synapse formed between antigen presenting cells (APCs) such as DCs and CD4+ T cells, which can even operate in the absence of productive infection of the donor APC." (PMID 35055987, 2021). "However, our findings suggest that successful HIV-1 transmission might not depend on the magnitude with which TF Envs mediate host cell entry of CD4+ cells, DC-SIGN binding and trans-infection but rely on another, as yet undefined, mechanism." (PMID 31978062, 2020). "Additionally, it has been reported that HIV-specific CD4 T-cell responses (IFN-γ, IL-2, TNF-α) during early infection or untreated infection may predict disease progression and effective viral control." (PMID 32941433, 2020). "Thus, CD4+ T cells remained stable in the LNs, with little to no variation at any point during infection." (PMID 32119719, 2020). "However, the concern about the enhancement of infection of some HIV-1 strains caused by sCD4- or CD4-containing molecule, like CD4-IgG2, cannot be excluded since no such study has been reported so far." (PMID 32523582, 2020). "Furthermore, in HIV-infected individuals failing to control infection, the co-expression of CD38 and PD-1 on CD4+ and CD8+ T cells could be a sign of T-cell activation." (PMID 32876566, 2020). "It is necessary that higher CD4+ T cells availability will be able to provide significantly higher assistance to CD8+ T cells and other immune cells in performing adequately enough to reduce intra-cellular parasite burden in order to block disease systems and completely clear the infection." (PMID 33187270, 2020). "In contrast to the rapidly fatal infections observed in IFN-γ–deficient mice, infections of mice lacking CD4+ T cells, with defective T cell survival, or compromised features of Th1 immunity (such as the key Th1-associated transcription factor T-bet−/−) reveal a more complex scenario." (PMID 32591391, 2020). "Importantly, we did not see a significant increase in the CD8+ or CD4+ IFN-γ T cell responses in the boosted GFP mice as compared to the GFP mice following primary infection." (PMID 33326500, 2020). "However, while our data suggests that infection of different memory CD4+ T cell subsets is reliant on the level of CCR5 expression, we cannot rule out other factors known to contribute to viral tropism including enhanced CD4 usage or fusogenicity." (PMID 32762760, 2020). "Similarly, the proportion of infection-elicited TNFα+, IL2+ and polyfunctional CD4+ T-cells was significantly higher among influenza A/H3N2-infected (p = 0.038, 0.017 and 0.041 respectively) and influenza B-infected patients (p = 0.002, 0.048 and 0.004 respectively) than in vaccine recipients." (PMID 32572168, 2020). "However, both CD4+ TH1 and TH17 cells elicit immune responses against M. tuberculosis, L. monocytogenes, Bordetella pertussis (B. pertussis), and S. aureus infections." (PMID 32858901, 2020). "CD4+ T cells on day 15 of infection also exhibited a significantly lower basal and maximal ECAR (a measure of glycolysis) than CD4+ T cells from day 5 of infection, indicating that CD4+ T cells lost glycolytic capacity concurrent with onset of functional exhaustion during infection." (PMID 32817333, 2020).
infection (continued). "In contrary to ART administrated at week 6 post infection, we did not detect any viral DNA in CD4 T cells from peripheral blood (data not shown) from RMs treated with ART at day 4, even in those (#R110806 and #111466R) that received a short course of treatment (respectively 7 and 10 days of ART)." (PMID 31723251, 2020). "Furthermore, all participants were treated according to new ARV guidelines where treatment is initiated much earlier, irrespective of CD4+ count or progressive stage of infection." (PMID 32129664, 2020). "As a result, macrophages are inefficiently infectable by most viral clones in vitro, in line with the observation that so-called “macrophage-tropic” viruses, which have a higher affinity for CD4 than their non-macrophage-tropic counterparts, only arise relatively late in in vivo infection." (PMID 32354203, 2020). "Furthermore, our data indicates that the detrimental effects of the host on the outcome of E. maxima infection is not due to immunosuppression, as demonstrated by the comparable CD4+:CD8+ ratios in both groups of infected chickens, TNi and HSi, during the first and second weeks of infection." (PMID 32612102, 2020). "Here we report the phenotypic and functional characterization of two RhCMV-specific CTL populations that do not become exhausted during chronic SIVmac239 infection of RMs, despite moderate levels of SIVmac239-induced immunosuppression via CD4+ T cell depletion." (PMID 32922404, 2020). "In contrast, infection of C57BL/6 mice with L. major induces a small lesion that is self-healing, a process linked with the differentiation of IFN-γ secreting Th1 cells and the absence of CD4+IL-4+ T cells." (PMID 33212818, 2020). "Thus, when analyses were combined, CD4+ T cells from day 15 of infection had a significantly diminished energetic profile and an increased OCR/ECAR metabolic ratio than cells from day 5 of infection." (PMID 32817333, 2020). "The ESAT-6-specific IL-17-, IFN-γ-, TNF-α-, and IL-2-producing CD4+ T-cell population in the lungs and spleen was considerably larger than that in BCG-immunised and BCG-primed ESAT-6-boosted mice, and Ag-specific CD4+CD44+ T-cells in the lungs were expanded when compared to pre-infection numbers." (PMID 32545304, 2020). "However, mice lacking CD4+ T cell still can survive from microsporidian infection, suggesting that CD4+ T cell is not a key immune defense against the infection." (PMID 32670257, 2020). "Interestingly, CD4 T cells treated with HIV-supernatants plus entry blockers, which inhibit active infection but retain the live virus in the culture media, exhibited a prolonged telomere length at day 3 and day 5 similar to early HIV-infected cells at day 3 compared to control cultures." (PMID 33643305, 2020). "The persistently present cryptococcus is what leads to the unregulated immune response as the CD4 recovers but may not particularly be reflected at the site of infection." (PMID 31964348, 2020). "γδ T cells are reportedly the primary source of IL-17 in early infection rather than CD4+ T cells." (PMID 32582168, 2020). "Consistent with the data showing a lack of an effect on peroxisome biogenesis factor levels, infection with HIV-1 harboring mutated Vpu did not significantly increase the expression of miR-500a-5p, miR-34c-3p, miR-93-3p, or miR-381-3p in HeLa-CD4/CXCR4/CCR5 cells, macrophages, or T cells." (PMID 32127461, 2020). "The expression of PD-1 on activated CD4+ T effector cells (CD3+CD4+CD44+CD62L−CD27−) and of PD-L1 on infiltrating monocytes (CD45+Ly6C+CD11b+) and resident macrophages (CD45+Ly6C−CD11b+F4/80+) were assessed in tissues from naïve WT mice and WT mice on days 12 and 35 post-infection (dpi)." (PMID 33193363, 2020). "Likewise, EBOV challenge studies using Cynomolgus macaques showed, using flow cytometry, that within the PBMC compartment CD4+, CD8+, and NK cell counts decreased dramatically following the first few days of infection, in contrast CD20+ B cell counts remained stable." (PMID 33679690, 2020).